CDK7 (cyclin dependent kinase 7)
Diseases named in the same sentence as CDK7 in open-access papers (continued):
Sharing a sentence is not in itself a finding about the gene and the disease.
chordoma (4 papers, 2022 to 2024). Chordomas are rare malignant tumors arising from embryonic remnants of the notochord in axial skeleton. "Nonetheless, CDK7/9 inhibition seems to provide an opportunity to target the cell viability of chordoma cells." (PMID 38786326, 2024). "CDK inhibitors such as THZ1, NVP-2 and THZ531 that inhibit CDK7, CDK9, CDK12 and CDK13, respectively, have been shown to downregulate SE-related oncogene expression and promote DNA damage response gene loss in chordoma and acute T-lymphoblastic leukaemia cells, respectively." (PMID 35514959, 2022). "CDK7 and CDK9 were shown to reduce the viability of chordoma cells through a genome-scale CRISPR/Cas9 approach as well as the large-scale testing of >450 small molecules." (PMID 38786326, 2024). "CDK inhibitors (particularly inhibitors of CDK7 and CDK9) have been shown to disrupt the autoregulatory landscape of brachyury, downregulate cellular brachyury levels in a limited number of chordoma cell lines, and reduce tumour growth in vivo." (PMID 38786326, 2024). "Taken together, CDK inhibition (predominantly CDK7 and CDK9 inhibition) is a suitable option for reducing TBXT expression in chordoma cell lines." (PMID 38786326, 2024). "CDK7 and CDK9 inhibition was lately identified as being effective in reducing viability in four chordoma cell lines, most likely due to a reduction in brachyury levels." (PMID 38786326, 2024). "Although the low number of clival chordoma cell lines narrows the statistical validity of the assumption that clival chordomas might be particularly prone to CDK7 inhibition, at least no specific resistance linked to the location of the tumour can be postulated." (PMID 38786326, 2024). "CDK7/12/13 inhibitor and the CA2 inhibitor, Dorzolamide, have been found to inhibit chordoma in vitro and in vivo." (PMID 36185236, 2022). "In this study, we determined the capability of the CDK7 inhibitor THZ1 and the CDK1/2/5/9 inhibitor dinaciclib to reduce TBXT expression at mRNA and protein levels in a broad range of nine cell lines that are models of primary, recurrent, and metastasised chordoma of the clivus and the sacrum." (PMID 38786326, 2024).
colon carcinoma (4 papers, 2013 to 2024). "As no specific inhibitor of CDK7 has been developed, Robert Fisher's group has replaced in HCT116 human colon carcinoma cells the two CDK7 alleles by a mutated CDK7 (F91G) that can be specifically inhibited by “bulky” adenine analogs (K7AS HCT116 cells)." (PMID 23737759, 2013). "In human colon cancer cells, Cdk7 T-loop phosphorylation is a two-step process in which phospho-S164 appears to be a prerequisite for T170 phosphorylation, revealing unexpected complexity in the regulation of Cdk7 activity in vivo." (PMID 39097586, 2024). "In this study, we demonstrated that siphonodictyal B inhibits several kinases such as CDK4/6, CDK7, and PIM2 in addition to PI3K in vitro and that siphonodictyal B exhibits more potent cytotoxic effects than liphagal against human colon cancer cell lines." (PMID 31364822, 2019).
esophageal cancer (4 papers, 2020 to 2024). A primary or metastatic malignant neoplasm involving the esophagus. "Recently, our team revealed a new function of CDK7 in mediating metabolic process of esophageal cancer." (PMID 38605321, 2024). "Inhibition of CDK7 was reported to suppress an adaptive response to lapatinib via transcription repression in gastric and esophageal cancer cell models." (PMID 31462705, 2020). "We discovered that CDK7 phosphorylated YAP at S127 and S397 sites in the nucleus and enhanced D-lactate dehydrogenase protein expression, therefore helping esophageal cancer stem cells escape from ferroptosis." (PMID 38605321, 2024). "Besides, the pharmacological inhibition of cyclin dependent kinase 7 (CDK7), bromodomain-containing protein 4 (BRD4) and histone deacetylases (HDACs), has been applied in esophageal carcinoma treatment." (PMID 36387198, 2022).
liver cancer (4 papers, 2019 to 2023). An epithelial or non-epithelial malignant neoplasm that arises from the liver. "Importantly, inhibition of p300, BRD4, CDK7 or MED1 reduces the expression of super-enhancer-associated oncogenes and exerts anticancer effects against liver cancer." (PMID 38135679, 2023). "The super-enhancer “writer” p300, super-enhancer “reader” BRD4, and super-enhancer activity regulators CDK7 and MED1 are often over-expressed in human liver cancer tissues, and their over-expression predicts poor patient prognosis." (PMID 38135679, 2023).
lung adenocarcinoma (4 papers, 2015 to 2021). A carcinoma that arises from the lung and is characterized by the presence of malignant glandular epithelial cells. "The results revealed that in lung adenocarcinoma, CDK7 is involved in the development of cisplatin resistance." (PMID 25411854, 2015). "Therefore, it is possible that CDK7 may be used as a gene therapy target for chemotherapy resistance in lung adenocarcinoma." (PMID 25411854, 2015). "However, RNA interference may partially reverse the CDK7-mediated drug resistance in lung adenocarcinoma cells." (PMID 25411854, 2015). "Using immunohistochemistry, the expression levels of PSMB6, HSPA9, DUT, CDK7, and PLK1 were found to be higher in lung adenocarcinoma tissues of patients, while the expression of FOLR2 was low, which was consistent with survival prediction." (PMID 34721732, 2021). "Here, we showed that selectively targeting CDK7 promoted apoptosis and suppressed NSCLC growth, which was validated in a lung adenocarcinoma PDX model." (PMID 32690037, 2020).
psoriasis (4 papers, 2022 to 2025). An autoimmune condition characterized by red, well-delineated plaques with silvery scales that are usually on the extensor surfaces and scalp. "Research reveals that disrupting Cdk7 signaling—through genetic approaches or small molecule inhibitors—attenuates disease development in mouse models of psoriasis-like inflammation." (PMID 40852730, 2025). "Emerging research highlights Cdk7 as a novel regulator of inflammatory T cell responses in psoriasis." (PMID 40852730, 2025). "CDK7 expression was markedly increased in CD4+ T cells from patients with psoriasis, and its inhibitor THZ1 ameliorated psoriasiform symptoms in an imiquimod-induced psoriasis-like mouse model." (PMID 37762693, 2023). "The strong link between ELOVL4 and IL36B, CDK7, CHMP2B, and S100A13 was also evident in RNA-Seq data sets of psoriasis lesional skin." (PMID 35900871, 2022). "For example, CDK7 was identified by proteomics, and then its related function was proved by further experience to reveal that the downstream mechanism CDK7 could promote CD4+ T-cell activation and Th17/Th1 cell differentiation by regulating glycolysis, contributing to the pathogenesis of psoriasis." (PMID 36338621, 2022).
T-cell acute lymphoblastic leukemia (4 papers, 2021 to 2025). Acute lymphoblastic leukemia of T-cell origin. "The covalent CDK7 inhibitor THZ1 showed potent efficacy in human T-cell acute lymphoblastic leukemia, which is dependent on transcription for maintenance of the oncogenic state." (PMID 33686962, 2021).
acute lymphoblastic leukemia (3 papers, 2021 to 2025). Leukemia with an acute onset, characterized by the presence of lymphoblasts in the bone marrow and the peripheral blood. "Due to the near perfect conservation of CDK9 and CDK7 between human and mouse, we were able to engineer these mutations in murine B-cell acute lymphoblastic leukemia (B-ALL) cells driven by the BCR-ABL oncogene in a homozygous Arf null background." (PMID 41279360, 2025). "Interestingly, SY-1365, a different Syros-developed targeted CDK7 inhibitor, markedly suppresses several solid cancers, including blood malignancies and breast cancer, ovarian cancer, small-cell lung cancer, AML, and acute lymphoblastic leukemia." (PMID 37501079, 2023).
breast tumor (3 papers, 2020 to 2021). "Both THZ1 and LDC4297 suppressed MCF-7 cells by slowing down cell proliferation and inducing apoptosis, which implied the potential breast tumor suppressive effect of CDK7 inhibitors." (PMID 34490348, 2021).
cholangiocarcinoma (3 papers, 2019 to 2021). A carcinoma that arises from the intrahepatic biliary tree (intrahepatic cholangiocarcinoma) or from the junction, or adjacent to the junction, of the right and left hepatic ducts (hilar cholangiocarcinoma). "Understanding the mechanism of CDK7 dependent transcriptional program in different subtypes of cholangiocarcinoma may be helpful to select appropriate patients for THZ1 treatment." (PMID 32174795, 2020). "By silencing CDK7 expression with siRNA, activity and proliferation of bile duct cancer cells were decreased, but this does not mean that THZ1 only exerts antitumor effects through CDK7 in all cholangiocarcinoma cells, especially in cholangiocarcinoma cells with higher IC50." (PMID 34422248, 2021).
lymphoma (3 papers, 2015 to 2019). A malignant (clonal) proliferation of B- lymphocytes or T- lymphocytes which involves the lymph nodes, bone marrow and/or extranodal sites. "Thus, CDK7 might be a suitable therapeutic target for inhibiting lymphoma, and QS1189 is a promising therapeutic option for various lymphomas and cells with acquired resistance to targeted therapy." (PMID 31076643, 2019). "In our study, CDK7 inhibition by QS1189 diminished bulk Ser2, Ser5, and Ser7 phosphorylation of the RNAPII CTD in MCL cells as well as other lymphoma cells." (PMID 31076643, 2019). "Here, we developed a new potent inhibitor targeting CDK7, QS1189, and investigated the efficacy and anticancer mechanisms this agent in MCL cells and various types of lymphoma cells." (PMID 31076643, 2019). "In conclusion, we developed the novel CDK7 inhibitor QS1189 as an attractive option for efficiently suppressing MCL and other lymphoma cells." (PMID 31076643, 2019). "In this study, we generated a potent inhibitor of cyclin-dependent kinase 7 (CDK7), designated QS1189, and confirmed its anti-cancer effects towards MCL and other lymphomas." (PMID 31076643, 2019). "Consequently, we showed that once CDK7 activity is suppressed, additional targeting of potential resistance mechanisms provides superior anti-lymphoma effect without increased toxicity to normal organs." (PMID 28134252, 2017).
medulloblastoma (3 papers, 2021 to 2024). A malignant, invasive embryonal neoplasm arising from the cerebellum. "THZ1 inhibits CDK7, CDK12, and CDK13 and was described as radiosensitizer in a study on medulloblastomas." (PMID 34063457, 2021). "The search for small molecules that might act upstream of the GPR56‐associated network led us to the CDK7/12/13 inhibitor THZ1, as it had been shown to overcome resistance to SMO antagonists in medulloblastoma by acting upstream and independent of SMO." (PMID 35253392, 2022).
melanoma (3 papers, 2019 to 2022). A malignant, usually aggressive tumor composed of atypical, neoplastic melanocytes. "In accordance, c-MYC has previously been implicated in suppression of BRAFV600E-induced senescence in melanocytes and melanoma progression, while loss of CDK7 results in senescence." (PMID 30651597, 2019). "Accordingly, MG132 treatment of melanoma cells caused an accumulation of CDK7 and rescued its expression under experimental depletion of MITF or c-MYC, the latter of which is an established target of several ubiquitin ligases." (PMID 30651597, 2019). "Across all melanoma lines tested, depletion of MITF was associated with a significant decrease in CDK7 transcription over time." (PMID 30651597, 2019). "Next, in silico ChIP-seq analyses revealed binding of MITF to an E box (tCACGTG) consensus sequence −86 base pairs upstream of the transcriptional start site of CDK7 in primary melanocytes, primary melanoma and melanoma cell lines." (PMID 30651597, 2019). "Our conclusions are thus limited by the poor selectivity of THZ1 and the role of CDK7 in transcriptional regulation, which may also contribute to melanoma growth." (PMID 36309522, 2022). "Moreover, the dependency of TFIIH-CAK on the melanocyte master regulator MITF or its structural homolog c-MYC extends the conceptional idea of a CDK7-targeted treatment approach to melanoma far beyond super-enhancers as determinants of oncogenesis." (PMID 30651597, 2019).
mesothelioma (3 papers, 2014 to 2022). A usually malignant and aggressive neoplasm of the mesothelium which is often associated with exposure to asbestos. "There are also several similarities with mesothelioma in this respect where overexpression of two or more of CDK7, GTF2H2, PCNA, RFC4, and the RFC5 were shared by the lung tumors." (PMID 25325012, 2014). "Then, we also found the NF2 loss is about 45.7% (32/70) of mesotheliomas, and YAP and CDK7 expressions are not correlated with NF2 loss in our mesothelioma TMA array (r = −.093, P = .443; r = −.062, P = .608, respectively) (Tables [Link], [Link], [Link])." (PMID 31755214, 2020). "Furthermore, lower expression of CDK7, AKT1, PARP1 (p < 0.1), CCND2 (cyclin D2), CDK2, CDK4, BIRC5 (survivin), PCNA and CDH2 (N-cadherin) (p < 0.005) have been shown to result in longer median survival of patients with mesothelioma." (PMID 36304150, 2022).
multiple myeloma (3 papers, 2020 to 2023). "Using a transcriptional CDK7 inhibitor, THZ1, coupled with H3K27ac ChlP-seq, we identified MAGI2 as a novel SE-associated gene of myeloma cells." (PMID 33579893, 2021). "Multiple Myeloma: Incubation of various multiple myeloma cell lines with seliciclib, a selective CDK2/E, CDK2/A, CDK7 and CDK9-inhibitor, resulted in apoptosis." (PMID 32380689, 2020). "Notably, transcription process and regulation of transcription were among the most significant gene ontology categories suppressed by THZ1 in myeloma cells, further indicating THZ1’s inhibitory effect on CDK7-dependent production of transcriptional regulators." (PMID 33579893, 2021).
renal cell carcinoma (3 papers, 2019 to 2022). "In this study, we investigated the role and therapeutic potential of CDK7 in regulating the angiogenic activity of endothelial cells and human renal cell carcinoma (RCC)." (PMID 31752390, 2019). "ICB = Immune checkpoint blockade, OV = oncolytic virus, ACT = adoptive T cell transfer, OVV = oncolytic virus vaccine, HDACi = class I histone deacetylase inhibitor, CDK7 = cyclin-dependent kinase 7, RCC = renal cell carcinoma." (PMID 33671881, 2021). "THZ1 used as a cyclin-dependent kinase 7 (CDK7) inhibitor reduces cell viability and induces apoptosis in human renal cell carcinoma." (PMID 36034776, 2022).
uveal melanoma (3 papers, 2019 to 2024). A melanoma derived from melanocytes of the uveal tract. "However, the synergistic effect of flavopiridol and an HDAC inhibitor, along with the anti-proliferative and pro-apoptotic action of a CDK7/9 inhibitor, was later demonstrated in uveal melanoma cell lines." (PMID 39598629, 2024).
chronic lymphocytic leukemia (2 papers, 2013 to 2019). "CDK7 may promote HIF1α transcriptional activity in chronic lymphocytic leukemia cell lines, and the expression of GLUT1, GLUT3, Hexokinase 1, and Hexokinase 2 is regulated by HIF1α43,44." (PMID 31784510, 2019). "In fact, the use of kinase inhibitor in clinical trials for the treatment of patients with chronic lymphocytic leukemia showed that the inhibition of CDK9- and CDK7-related pathways was responsible for the decrease of the antiapoptotic factor Mcl-1." (PMID 23840966, 2013).
HCMV infection (2 papers, 2016 to 2022). "This concept has been substantiated by providing evidence for the high and multifaceted importance of CDK7 and CDK9 in HCMV infection." (PMID 27548200, 2016).
malignant pleural mesothelioma (2 papers, 2020 to 2021). A malignant neoplasm that arises from mesothelial cells in the pleura and shows a diffuse growth pattern. "An independent study revealed a good correlation between CDK7 and Yap protein levels in malignant pleural mesothelioma (MPM) and showed that knockdown of CDK7 in MPM cells reduced Yap level, tumor cell migration and invasion, as well as tumor sphere formation." (PMID 33869224, 2021). "Here, we investigated the role of CDK7 on YAP regulation in human malignant pleural mesothelioma (MPM)." (PMID 31755214, 2020). "Malignant pleural mesothelioma cell lines with relative higher CDK7 expression showed higher GTIIC reporter activity." (PMID 31755214, 2020).
mantle cell lymphoma (2 papers, 2019 to 2024). Mantle cell lymphoma is a rare form of malignant non-Hodgkin lymphoma affecting B lymphocytes in the lymph nodes in a region called the ``mantle zone''. "Venetoclax-resistant derived HBL-2 mantle cell lymphoma cells were sensitive to CDK7 inhibition with THZ1, which also prevented the emergence of venetoclax-resistant HBL-2 clones." (PMID 38893249, 2024).
ovarian tumors (2 papers, 2024 to 2025). "CDK7 is involved in cell-cycle progression, and CDK7 inhibitors have been shown to exert broad cytotoxicity against ovarian tumors." (PMID 40981433, 2025). "The CDK7 inhibitor also demonstrated significant cytotoxicity against ovarian tumors." (PMID 38255960, 2024).
rheumatoid arthritis (2 papers, 2018 to 2024). A chronic, systemic autoimmune disorder characterized by inflammation in the synovial membranes and articular surfaces. "Similar to our data, another CDK7 inhibitor BS-181 also inhibits the expression of IL-6 and the inflammation of rheumatoid arthritis." (PMID 38540292, 2024). "To further elucidate the universal effect of CDK7 on rheumatoid arthritis synovial fibroblast cells, we isolated and cultured fibroblast‐like synovial cells from CIA mice's joints." (PMID 29083085, 2018). "It is worthy to further study whether the combination of other CDK7 inhibitor and DMARDs is effective in rheumatoid arthritis." (PMID 29083085, 2018).
T-cell lymphomas (2 papers, 2017). "Here, we addressed an unmet therapeutic need by identifying CDK7 as a novel target for most common aggressive T-cell lymphomas, PTCL-NOS and ALCL-ALKneg." (PMID 28134252, 2017). "Here, the authors show that the THZ1, a CDK7 inhibitor, suppresses STAT transcriptional activity leading to apoptosis and sensitization to BCL2 inhibitors in T-cell lymphomas." (PMID 28134252, 2017).
adenoma (1 paper, 2022). A neoplasm arising from the epithelium. "CDK9 and CDK18 were upregulated in NR5A1-adenomas, whereas CDK4 and CDK7 were upregulated in POUF1-adenomas." (PMID 35260162, 2022).
anaplastic thyroid carcinoma (1 paper, 2021). "Increased expression of PPP1R15A and CDK7 is positively associated with undesirable clinical prognosis in anaplastic thyroid carcinoma." (PMID 34722892, 2021). "CDK7 and PPP1R15A are considered potential biomarkers and therapeutic targets for anaplastic thyroid carcinoma." (PMID 34722892, 2021).
atherosclerosis (1 paper, 2022). A disease characterized by the build-up of fatty material and calcium deposition in the arterial wall resulting in partial or complete occlusion of the arterial lumen. "The biological function and their roles in atherosclerosis progression for the other genes, including DAZAP2, ARL6ip, CDK7, LIMS, HBP1, and DNAJB6, remain to be investigated." (PMID 35795669, 2022).
B-cell lymphoma (1 paper, 2022). "Furthermore, genes like CDK7, NRF2, and PARP1 are established chemoresistance markers for various therapies in B-cell lymphoma." (PMID 36058921, 2022).
brain ischemia (1 paper, 2023). Diminished or absent blood supply to the brain caused by obstruction (thrombosis or embolism) of an artery resulting in neurologic damage. "While all these molecules inhibit (at least partially) Cdk7, no studies have investigated the potential involvement of Cdk7 in brain ischemia." (PMID 37108171, 2023).